OR4A5 (olfactory receptor family 4 subfamily A member 5)
Description:
Odorant receptor.
Synonyms: OR11-111
Tractability: Antibody: UniProt places it where antibodies can reach, with medium confidence; UniProt predicts a signal peptide or a membrane-spanning region; its Gene Ontology location is reachable by antibodies, with medium confidence.
Gene: Protein-coding gene on chromosome 11 (54,706,832 to 54,707,902, forward strand). Ensembl gene ENSG00000221840.
Subcellular location: Cell membrane
Pathways (Reactome):
Sensory Perception: Expression and translocation of olfactory receptors
Gene Ontology:
Molecular function: olfactory receptor activity; G protein-coupled receptor activity
Biological process: detection of chemical stimulus involved in sensory perception of smell; G protein-coupled receptor signaling pathway
Cellular component: plasma membrane; membrane
Genetic constraint (gnomAD): Missense variants: 587 observed, 334.31 expected, observed/expected ratio (o/e) 1.76, 90% interval 1.64 to 1.88. Synonymous variants: 216 observed, 119.56 expected, observed/expected ratio (o/e) 1.81, 90% interval 1.61 to 1.96.
Homologues: Orthologues: macaque OR4A5 (85% identical), dog OR4A39 (74% identical), mouse Or4a39 (73% identical), rat Olr703 (72% identical), mouse Or4a78 (69% identical), mouse Or4a80 (69% identical), rat Or4a78 (68% identical), mouse Or4a73 (68% identical), rat Olr716 (66% identical), rat Or4a71 (66% identical), rat Or4a73 (66% identical). Paralogues in human: OR4A8 (75% identical), OR4A16 (70% identical), OR4A47 (64% identical), OR4A15 (63% identical), OR4C46 (58% identical), OR4C3 (57% identical), OR4C15 (57% identical), OR4C13 (56% identical), OR4C5 (55% identical), OR4C12 (55% identical), OR4C45 (55% identical), OR4C6 (54% identical), and 116 more.